MET (MET proto-oncogene, receptor tyrosine kinase)
Diseases named in the same sentence as MET in open-access papers (continued):
Sharing a sentence is not in itself a finding about the gene and the disease.
cancer (continued). "HGF is known to have important roles in cancer progression through its specific receptor, MET." (PMID 27612426, 2016). "MET/HGF has been regarded as a promising therapeutic target in cancer treatment, whose gene or protein status may be indicative of patient response to MET-targeted drugs." (PMID 27013592, 2016). "This TKI drug binds to several TK receptors, which are often over expressed in a lot of cancer cell types, including hepatocyte growth factor receptor (MET), RET (rearranged during transfection), and simultaneously inhibits angiogenic factor receptor as VEGFR-1, VEGFR-2, and VEGFR-3." (PMID 27881963, 2016). "Yet, whether patients suffering from cancers showing abundant membranous MET immunoreactivity could benefit from treatment with MET inhibitors needs further investigation." (PMID 26909606, 2016). "MET gene amplification was found in about a third of EBV-positive cancers." (PMID 25613731, 2015). "Aberrant MET signaling contributes to the initiation and progression of cancer." (PMID 25965822, 2015). "To date, the only US FDA-approved MET pathway-related agents, crizotinib and cabozantinib, are dual- or multi-tyrosine kinase inhibitors, indicating that blocking MET jointly with other cancer-related pathways might be more beneficial for cancer treatment." (PMID 28536405, 2015). "Thus, silencing of two major functional domains that regulate HGF/c-MET signaling represents a promising therapeutic strategy in targeting this driver of cancer." (PMID 25726528, 2015). "Other reports have shown that miR-199a-3p targets MET in several cancer cell lines [5, 16, and 31]." (PMID 25839163, 2015). "c-MET pathway activation is also postulated to promote cancer metastasis by inducing epithelial-to-mesenchymal transition (EMT), which causes epithelial cells to lose E-cadherin and cell-to-cell contact and acquire mesenchymal characteristics such as motility and invasion." (PMID 28943627, 2015). "For all above reasons MET could become a valuable target for cancer therapy and several drugs targeting MET or its ligand HGF are currently undergoing early phase clinical trials in various cancers." (PMID 26580964, 2015). "Thus, inhibition on HGF-initiated MET signaling pathway would provide a new approach to cancer targeted therapeutics." (PMID 26254225, 2015). "Since downregulation of MET or Axl has been shown to induce both apoptosis and autophagy in different cancer types, we asked whether miR-34a induces autophagy in addition to apoptosis in PCa cells." (PMID 26313360, 2015). "Consistent with our work, a previous study observed that MET-addicted cancer cells could be rescued by ligands of FGFR from crizotinib sensitivity." (PMID 26528757, 2015). "Taken together, although high HGF levels might indicate enhanced activation of the MET signaling pathway in cancer development, these data should be cautiously interpreted due to their limited predictive value for clinical response." (PMID 28536405, 2015). "In support of these findings, treatment with ART down-regulated the expression of multiple molecules associated with maintaining cancer stemness and metastatic potential, including c-MYC, epidermal growth factor receptor (EGFR), c-MET, Src, and focal adhesion kinase (FAK)." (PMID 26426994, 2015). "Potentially, pharmacological agents that disrupt the HUWE1-TIAM1 interaction could be beneficial in decreasing the HGF/MET-driven metastatic dissemination of cancer cells." (PMID 25543140, 2015). "Therefore, development of agents targeting to components in HGF/MET pathway is a potential therapeutic strategy for many cancers." (PMID 26254225, 2015). "Thus we provide proof of concept for a new class of MET inhibitors for cancer therapy, namely small-molecule receptor antagonists." (PMID 30090230, 2015).
cancer (continued). "In malignant tumors, HGF is produced by stromal cells, while its receptor c-MET is expressed by cancer cells, which in the mid-1990s led to the hypothesis that this paracrine loop might determine malignant behaviors." (PMID 28536400, 2015). "MET inhibition is an attractive opportunity for molecularly targeted cancer therapy." (PMID 25473895, 2015). "We therefore set to identify potential mediators of resistance to MET inhibition in cancer cells." (PMID 25473895, 2015). "In light of these studies and our results, we speculate that radiotherapy of GBM could engender clones of MET-amplified cancer cells that drive tumor recurrence." (PMID 26909358, 2015). "Taken together, these data suggested that ψ-Bufarenogin could be a promising drug candidate in HCC therapy particularly in the personalized treatment of HCCs in which EGFR/c-MET-driven signaling is indispensable for cancer progression." (PMID 25890498, 2015). "Furthermore, information on testosterone levels in patients taking ALK inhibitors targeting other alterations in cancer, for example MET and ROS, should also be gathered." (PMID 25955180, 2015). "Moreover, the therapeutic rationale of dual targeting of HGF/c-MET and other signaling pathways by small molecules is a current option for many cancers." (PMID 28536400, 2015). "Furthermore, MET has been used as a target to improve cancer therapy and ameliorate the sensitivity of chemotherapy in different cancers." (PMID 25874496, 2015). "However, while miR-200 is downregulated in some cancers, upregulation of miR-200c has been found in multiple tumors indicating that miR-200c may also exhibit oncogenic potential, likely due to miR-200c overexpression increasing metastatic risk by the induction of MET." (PMID 26556949, 2015). "Considering that the dimerization of RTKs is important for controlling their biological function in the context of cancer, crosstalk between c-MET and other RTKs should be investigated carefully if we are to understand the role of c-MET in human cancer progression." (PMID 26225770, 2015). "High MET gene copy number was more frequently identified in cancers (e.g., NSCLC)." (PMID 28536405, 2015). "MET is involved in many mechanisms of cancer proliferation and metastasis." (PMID 24500024, 2014). "In addition, MET also contributes to cancer resistance against EGFR inhibitors through bypass signaling." (PMID 24500024, 2014). "Furthermore, MET activation in cancer is often ligand-independent, deriving from genetic lesions as activating mutations, gene amplification, or post-transcriptional modifications." (PMID 28548076, 2014). "Expression of HGF and/or its receptor MET is increased in a wide variety of cancers." (PMID 28548073, 2014). "Certain studies have shown that miR-449 could directly target and switch off the expression of GMNN, MET, CCNE2 and another cancer-related genes, the majority of which are associated with the cell cycle, by syncretizing with the 3′UTR of target genes." (PMID 25202363, 2014). "It has been documented that HGF/c-MET are involved in cancer cell proliferation and invasion." (PMID 24797571, 2014). "The combination of erlotinib and tivantinib (MET inhibitor) in NSCLC showed clinical activity in patients with KRAS-mutated cancers, even though the endpoints of the trial were not achieved." (PMID 24722523, 2014). "Furthermore, it paves a promising way to understand how c-MET pathway is involved in carcinoma metastasis." (PMID 25245029, 2014). "An intragenic L1-ASP has been shown to act as an alternate promoter in cancer driving the transcription of a truncated and oncogenic isoform of the c-MET gene, and the ability of retrotransposons to act as alternative promoters for protein coding genes has been reported." (PMID 23703216, 2013). "In contrast, HGF plays common roles in cancer metastasis, independent of the presence or absence of MET mutations." (PMID 23296269, 2013).
cancer (continued). "Consequently, MET overexpression relative to normal tissue has been detected in various types of cancers." (PMID 24265843, 2013). "It is well known that c-MET plays important roles in cancer development through its proliferation- and angiogenesis-promoting effects exerted by downstream oncogenic pathways, and metastasis-promoting effect which is mainly dependent on metalloprotease production." (PMID 24205104, 2013). "MET is a receptor tyrosine kinase that is activated by the ligand HGF and has been shown to be constitutively expressed, mutated, or over-expressed in many different cancer cell types." (PMID 24326130, 2013). "In addition, overexpression of MET is indicative of increased tumor aggressiveness and poor prognosis in cancer patients." (PMID 24265843, 2013). "Among these agents, Crizotinib (PF-02341066) is an orally bioavailable, ATP-competitive, small-molecule inhibitor of c-MET and anaplastic lymphoma kinase, and is considered a very potential agent for treatment of cancers dependent on these oncogenic kinases for growth and survival." (PMID 23379953, 2013). "Thus, mTOR inhibitors achieve growth inhibition by suppressing both survival signals from EGFR and resistance signals from MET in cancer cells." (PMID 23690929, 2013). "c-MET is frequently expressed in a variety of other cancers." (PMID 23251249, 2013). "Such sequential downstream events of MET signaling are contributable for cancer cell motility." (PMID 23296269, 2013). "Using LMH 80 and non-permeating immunofluorescence, we could definitively establish that p170 c-MET is expressed on cell surface of human cancer cells, in agreement with previous studies in human SkHep1 and LoVo cell lines." (PMID 22511956, 2012). "Additionally, there is convincing evidence from murine derived cancer cells that p170 c-MET is exposed at the cell surface, and can be activated by HGF." (PMID 22511956, 2012). "Since c-Met protein overexpression due to mRNA upregulation occurs predominantly in human cancers, the basal level of phosphorylated c-Met in PC-3 cells may simply be a result of increased MET transcripts via unknown mechanisms." (PMID 22639908, 2012). "This process could be inactivated in cancer cells, which are often unable to unleash the apoptotic pathway, leading to MET accumulation, and further support of anti-apoptotic signals." (PMID 22973229, 2012). "Moreover, we also demonstrated that a NaBu- resistant population expressed a high level of c-MET with cancer stem cells property." (PMID 22253909, 2012). "Moreover, we showed that inhibition of MET shedding by TIMP-1 occurs also in cancer cells, thus sustaining their invasive growth potential and ability to colonize the liver." (PMID 22973229, 2012). "MET oncogene overexpression has been described in a variety of human cancers including prostate." (PMID 22639908, 2012). "Furthermore, the endogenous expressing c-MET contributes to the survival of cancer stem cell population from the treatment of NaBu." (PMID 22253909, 2012). "Thus, the targeting of HGFR/c-MET can potentially be used as a strategy for destroying refractory drug-resistant cancer cells." (PMID 22606042, 2012). "Given the high c-MET levels in MKN-45 and SGC7910 cell lines, we hypothesize that anti-c-Met/PE38KDEL can attenuate cancer cell growth through inhibition of protein synthesis via c-Met inhibition." (PMID 21733192, 2011). "The anti-cancer effect of IT occurred primarily through inhibition of protein synthesis, and caspase-3-mediated apoptosis, suggesting the potential value of IT as an anti-c-MET therapeutics for GC." (PMID 21733192, 2011). "MET is constitutively activated as a proto-oncogenic receptor tyrosine kinase, which promotes invasion and migration by activating a variety of signal transduction pathways in numerous types of carcinomas." (PMID 22140553, 2011). "Cancer cell lines bearing MET gene amplification have been found to be "addicted" to MET." (PMID 20500904, 2010).
cancer (continued). "Expression of miR-199a/a* is silenced in all proliferating cell lines tested except fibroblasts; introduction of miR-199a/a* caused apoptosis in cancer cells; miR-199a* down-regulates MET proto-oncogene and also down-regulates ERK2, an effector downstream of MET." (PMID 20302635, 2010). "For instance, structurally conserved RET-M918T and MET-M1250T cancer drivers are situated in the substrate binding C-lobe of the kinase core and are known to be associated with oncogenic activation by displaying the highest transforming potential among known RET and MET mutations." (PMID 19834613, 2009). "There are examples of cancer mutations displaying a subgroup level of conservation, including EGFR-L858 position, which bears a conserved leucine in EGFR and ABL kinases, or a conserved aspartate shared in FLT3, KIT, MET, PDGFRα." (PMID 19834613, 2009). "However, dysregulated activation of HGF/c-MET axis contributes to the development and progression of numerous human cancers, such as gastroesophageal adenocarcinoma, cholangiocarcinoma, colon cancer, renal cell carcinoma, glioblastomas, and lung cancer, among others." (PMID 40520181, 2025). "However, whether MET autoantibodies are produced in patients with cancer, and what is their function, are currently unknown." (PMID 40401526, 2025). "Therefore, targeting these pathways may offer therapeutic strategies for managing cancers, especially those characterized by aberrant c-MET signaling and downstream effects." (PMID 40149618, 2025). "Furthermore, MET is known to be upregulated in response to environmental stresses such as hypoxia or irradiation, highlighting its role in adaptive resistance mechanisms that contribute to therapeutic challenges in cancer treatment." (PMID 39774381, 2025). "Moreover, further research on MET expression and its role in cancer prognosis could lead to the development of new therapeutic targets." (PMID 39991569, 2025). "In these cancers, we would predict that TMEM127 loss has similar effects on membrane dynamics, membrane protein accumulation, and CCP formation to those seen in our model and that accumulation of other growth factor receptors, such as MET, on the cell surface will lead to transformation." (PMID 38687678, 2024). "Previous studies have confirmed that MET is a significant driver of mutation in NSCLC, activating signaling pathways downstream of PI3K/AKT, Ras-MAPK, and STAT3 (signal transducer and activator of transcription 3), which promote cancer proliferation, migration, and invasion." (PMID 39201787, 2024). "Similarly, pan-HER inhibitors and TNKS1/2 inhibitors are being evaluated in clinical trials as monotherapy or in combination with other drugs, such as MET inhibitors, in patients with advanced cancers or disease progression after >2 previous treatment regimens." (PMID 39551860, 2024). "Given the importance of juxtamembrane (JM) regions in controlling the active-state of many RTKs and the prevalence of exon 14 skipping within the JM of MET in cancer, we were interested in how patterns of mutational sensitivity from the DMS could relate the JM to potential MET regulatory mechanisms." (PMID 39268701, 2024). "During cancer progression, majority of cancer cells were putatively clones of minority by MET exon 14 clones, with diminished clones with FGF-FGFR or WNT, ERBB2, MAPK pathways, which may lead less FGFR-Activated or Bypass-Activated subtype in more advanced disease stages." (PMID 39060379, 2024). "In cases of non-hereditary cancer, somatic mutations in the MET gene are infrequent." (PMID 39458991, 2024). "Together, the expression of the MET gene could be regulated by ERs in cancer cells." (PMID 39742369, 2024). "Additionally, inhibition of Met using a MET inhibitor (PHA-665752) has been found to decrease the expression of glycolysis initiation-associated hexokinase 2 (HK2) and promote the reactivation of oxidative phosphorylation in cancer cells within a NSCLC model." (PMID 39201787, 2024).
cancer (continued). "The MET oncogene, encoding the hepatocyte growth factor (HGF) receptor, drives invasive growth, a genetic programme largely overlapping with the epithelial-to-mesenchymal transition and governing physiological and pathological processes such as tissue development and regeneration, as well as cancer." (PMID 38203718, 2023). "In addition, we observed, that in HMVII cell line treated with foretinib as monotherapy, the pEGFR/EGFR ratio was increased, which may indicate that cancer cells compensate for the decreased pMET/MET ratio by increasing the pEGFR/EGFR ratio." (PMID 37679999, 2023). "Moreover, our findings pertain mainly to MET-addicted cells with high MET amplification and MET-activating mutations, yet this level of MET dependency is often not observed in cancers with lower level of MET amplification or MET overexpression." (PMID 37188738, 2023). "Not all alterations of the MET gene are considered driver mutations in cancers." (PMID 36829199, 2023). "Furthermore, MET was involved in proteoglycans in cancer in GC." (PMID 35280778, 2022). "Binding of HGF to its receptor MET stimulates cancer cells through the phosphorylation of the HGF/MET signaling pathway, leading to downstream activation of multiple cytokines implicated in cellular motility, proliferation, angiogenesis, and invasive growth of cancer cells." (PMID 34997350, 2022). "A previous study reported that neutrophils could acquire immunosuppressive characteristics in T cell-inflamed cancers, and the efficacy of cancer immunotherapies was improved via c-MET inhibition by impairing neutrophil mobilization and recruitment into tumors." (PMID 34986867, 2022). "The presence of activating mutations in MET, as well as gain of chromosome 7, where the MET gene is located, are the most common genetic alterations associated with PRCC, leading to the clinical evaluation of MET tyrosine kinase inhibitors (TKIs) in this cancer." (PMID 35754026, 2022). "Thus, it is complicated to target just the HGF/MET pathway in cancer therapy." (PMID 35986321, 2022). "Therefore, the Grb2-SH2 domain and Gab1-MBD motif might function as epitope peptides to block the interaction of endogenous Grb2 or Gab1 with c-MET, thereby limiting the proliferation of cancer cells." (PMID 36233320, 2022). "MACC1 is directly associated with the regulation of c-MET expression, subsequently inducing EMT via elevated HGF/c-MET signalling, but also of the pluripotency marker NANOG and the cell adhesion factor SPON2, both contributing to cancer progression and metastasis." (PMID 35597866, 2022). "Hence, dysregulated MET expression is involved in a variety of human cancers including HCC." (PMID 36430594, 2022). "Thus, targeting PAN may represent a mechanism for the selective regulation of the c-MET pathway, with relevance to cancer treatment." (PMID 35778602, 2022). "MET, AM25C, MROH9, MYEOV, FAM111B, Y6D, and PPP2R3A were highly expressed in the high-risk group, indicating that these genes may be related to the oncology process for patients with PAAD, and they seemed to be cancer-promoting genes." (PMID 35077391, 2022). "Additionally, MET amplification was found in nine types of cancer." (PMID 36483096, 2022). "Therefore, the MET signaling pathway is considered a potential therapeutic target, and inhibition of this pathway may be used for the targeted treatment of cancer." (PMID 34568049, 2021). "Notably, we further identified multiple reported malignancy‐related genes (e.g., MET, PIK3R1, PRKCA, PTEN, SHC1, and STAT3) upregulated in HCC272, and demonstrated that these genes were mainly enriched for cancer‐related functions, which were associated with broad drug resistance." (PMID 34105295, 2021). "cfChIP targeting somatic cancer mutations is a promising new methodology for which the basis of liquid biopsies could help understand how expression of mutated oncogenic drivers such as EGFR, ALK, MET and KRAS contribute to carcinogenesis." (PMID 34453867, 2021).